ARID4B (AT-rich interaction domain 4B)
Description:
Acts as a transcriptional repressor. May function in the assembly and/or enzymatic activity of the Sin3A corepressor complex or in mediating interactions between the complex and other regulatory complexes. Plays a role in the regulation of epigenetic modifications at the PWS/AS imprinting center near the SNRPN promoter, where it might function as part of a complex with RB1 and ARID4A. Involved in spermatogenesis, together with ARID4A, where it functions as a transcriptional coactivator for AR (androgen receptor) and enhances expression of genes required for sperm maturation. Regulates expression of the tight junction protein CLDN3 in the testis, which is important for integrity of the blood-testis barrier. Plays a role in myeloid homeostasis where it regulates the histone methylation state of bone marrow cells and expression of various genes involved in hematopoiesis. May function as a leukemia suppressor (By similarity).
Synonyms: BRCAA1; RBBP1L1; RBP1L1; SAP180; BCAA
Tractability: PROTAC: UniProt records ubiquitination sites on it; ubiquitination databases record sites on it; its protein half-life has been measured.
Gene: Protein-coding gene on chromosome 1 (235,131,634 to 235,328,219, reverse strand). Ensembl gene ENSG00000054267.
Subcellular location: Nucleus; Cytoplasm
Subcellular location (Human Protein Atlas): Cytosol; Mitochondria; Nucleoplasm
Pathways (Reactome):
Chromatin organization: HDACs deacetylate histones
Disease: Potential therapeutics for SARS
Gene expression (Transcription): NoRC negatively regulates rRNA expression
Gene Ontology:
Molecular function: DNA binding; protein binding; transcription cis-regulatory region binding
Biological process: negative regulation of cell migration; negative regulation of stem cell population maintenance; negative regulation of transcription by RNA polymerase II; negative regulation of transforming growth factor beta receptor signaling pathway; positive regulation of stem cell population maintenance; regulation of transcription by RNA polymerase II
Cellular component: cytoplasm; cytosol; nucleoplasm; nucleus; Sin3-type complex
Genetic constraint (gnomAD): Loss-of-function variants: 9 observed, 89.11 expected, observed/expected ratio (o/e) 0.1, 90% interval 0.06 to 0.18. The upper end of that interval is the gene's LOEUF score, 0.18, which puts it in group 1 of 6, group 1 being the genes least tolerant of losing a copy. Missense variants: 873 observed, 1,126.3 expected, observed/expected ratio (o/e) 0.78, 90% interval 0.73 to 0.82. Synonymous variants: 375 observed, 393.22 expected, observed/expected ratio (o/e) 0.95, 90% interval 0.88 to 1.04.
Homologues: Orthologues: chimpanzee ARID4B (99% identical), macaque ARID4B (99% identical), rabbit ARID4B (95% identical), dog ARID4B (95% identical), guinea pig ARID4B (93% identical), rat Arid4b (90% identical), mouse Arid4b (90% identical), pig ARID4B (88% identical), tropical clawed frog arid4b (62% identical), zebrafish arid4b (52% identical), Caenorhabditis elegans arid-1 (20% identical), Drosophila melanogaster htk (15% identical). Paralogues in human: ARID4A (43% identical), ARID5B (13% identical), ARID5A (8% identical).
Diseases named in the same sentence as ARID4B in open-access papers:
ARID4B is named in the same sentence as 51 diseases in open-access papers, as found by Europe PMC text mining. Sharing a sentence is not in itself a finding about the gene and the disease. The quoted sentences say what the papers report.
breast cancer (14 papers, 2011 to 2025). A primary or metastatic malignant neoplasm involving the breast. "Since the function of ARID4B seems important in several cancer types, this study aimed to analyze the effect of loss-of-function in human breast cancer cells and to evaluate the pathways deregulated by the impact of the loss-of-function of the ARID4B gene." (PMID 38137006, 2023). "In conclusion, the ARID4B gene is associated with some aggressive phenotypes in breast cancer cells." (PMID 38137006, 2023). "V5-tagged AKR and DBA alleles of Arid4b were ectopically expressed in the mouse mammary carcinoma cell line Met-1, which was originally derived from tumors arising in the MMTV-PyMT transgenic model." (PMID 22693453, 2012). "The present study demonstrated that loss-of-function mutations close to a frequently mutated position of the ARID4B gene diminish its expression and alter the transcriptome program, reducing some aggressive characteristics of breast cancer, such as proliferation, viability, and migration." (PMID 38137006, 2023). "In our previous work, we screened out and cloned BRCAA1 gene (breast cancer associated antigen 1 gene) from breast cancer cell line MCF-7cells [AF208045, also called ARID4B (AT-rich interactive domain-containing protein 4B)], and identified its antigen epitope peptide SSKKQKRSHK." (PMID 21612621, 2011). "Arid4b was identified as a candidate gene of interest through linkage and expression correlation analyses, and the in vitro and in vivo data presented here provide the first direct evidence of a causal role of Arid4b in mammary tumor progression and metastasis." (PMID 22693453, 2012). "Allelic variation and the differential expression of ARID4B attributed to mammary tumor growth and metastasis in ER+ breast cancer." (PMID 40558499, 2025). "Recently, increased ARID4B expression was reported to correlate with unfavorable clinical outcomes in patients with breast cancer." (PMID 40558499, 2025). "The potential involvement of ARID4B in breast cancer was first suggested by the physical interaction between ARID4B and BRMS1 (breast cancer metastasis suppressor)." (PMID 40558499, 2025). "In breast cancer, studies have been performed on mouse cells in which an ectopic expression of the ARID4B gene has been introduced, and an increase in proliferative and migratory capacities has been found." (PMID 38137006, 2023). "ARID4B is an activator of the PI3K-AKT pathway, an oncogene in PTEN-deficient prostate cancer and amplified in 12% of breast cancers in the TCGA data set." (PMID 33921698, 2021). "So the effect of ARID1B and ARID4B in breast cancer served as oncogenes in the previous and present study." (PMID 33592583, 2021). "Based on the analysis of depleted gRNAs, we identified ERGs associated with cell cycle and cell senescence, and these ERGs showed higher rate of copy number amplification or up-regulation in breast cancer (i.e., ARID4B and EZH2)." (PMID 32963031, 2020). "In the current study, we employ the MMTV-PyMT transgenic mouse model and the AKXD panel of recombinant inbred mice to identify AT–rich interactive domain 4B (Arid4b; NM_194262) as a breast cancer progression modifier gene." (PMID 22693453, 2012). "The presence of putative DNA and histone binding domains in the N-terminal half of ARID4B suggest that its influence on mammary tumor progression involves directing the HDAC activity of mSIN3A complexes to chromatin." (PMID 22693453, 2012). "Consistent with our genetic analysis and in vivo experiments in our mouse model system, ARID4B expression was also an independent predictor of distant metastasis-free survival in breast cancer patients with ER+ tumors." (PMID 22693453, 2012). "Bioinformatics analysis identified Arid4b as the top target of miR-290, suggesting that miR-290 might suppress breast cancer’s progression by targeting Arid4b." (PMID 40558499, 2025).
breast cancer (continued). "Apart from this, several studies demonstrated that ARID4B plays a significant role in cancer development, metastasis, and cancer-related signaling pathways in different types of human cancers, including breast cancer, ovarian cancer, and hepatocellular carcinoma." (PMID 37686014, 2023). "Here, ARID1B mRNA expression was associated with poor prognosis in HER2-riched breast cancers and lymph node-positive patients, ARID4B mRNA expression, which was higher in breast cancer tissues, was interrelated with unfavorable prognosis in all breast cancer patients." (PMID 33592583, 2021). "Further genomic analysis of human breast cancers revealed that MRCKα is frequently co-amplified with the oncogenes ARID4B and AKT3 which might contribute to the prognostic value of MRCKα expression." (PMID 33921698, 2021). "High expression of ARID4B was associated with an approximately 2-fold increased risk of metastatic progression in human breast cancer patients who were lymph node negative at diagnosis." (PMID 22693453, 2012). "Because Met-1 cells are poorly metastatic in our laboratory, and because we were unable to stably overexpress Arid4b in several more aggressive mouse breast cancer cell lines, we adopted a knockdown strategy to examine the role of Arid4b in lung metastasis in vivo." (PMID 22693453, 2012). "Indeed, there are multiple lines of evidence implicating Arid4b in breast cancer." (PMID 22693453, 2012). "The mRNA expression of ARID1B (p=0.0375), ARID4B (p=0.0086), JARID1B (p=0.0003) and JARID1D (p=0.0138) were interrelated with worse survival in breast cancer patients with positive lymph node." (PMID 33592583, 2021). "Interestingly, ARID4B, MRCKα and AKT3 are mostly amplified together and show a highly significant co-occurrence of genetic alterations in breast cancer." (PMID 33921698, 2021). "Furthermore, the correlation of MRCKα expression with breast cancer formation and progression appears to be at least partly due to the co-amplification with AKT3 and in particular ARID4B." (PMID 33921698, 2021). "Among the genes identified, ARID4B was reported as a prometastatic gene and served as an independent predictor of disease outcome in breast cancer, while its expression was not correlated with OC patient survival." (PMID 27081703, 2016). "Stable shRNA-mediated knockdown of Arid4b significantly inhibited the pulmonary metastatic efficiency of orthotopic mammary tumors without inhibiting primary tumor growth." (PMID 22693453, 2012). "The low mRNA expression of ARID1B (p=0.0023), ARID2 (p=0.0439), ARID4A (p=0.0056), ARID4B (p=0.0317), ARID5B (p=0.00054), JARID1D (p=0.043), JARID2 (p=0.0068) were interrelated with poor survival in breast cancer patients with negative lymph node." (PMID 33592583, 2021). "The expression of ARID1A, ARID1B, ARID2, ARID3A, ARID4A, and ARID4B in no-luminal subtypes was lower than luminal subtypes, however, ARID3C, ARID5A, and JARID2 mRNA expression were higher in no-luminal subtypes of breast cancer tissues." (PMID 33592583, 2021).
gastric cancer (7 papers, 2011 to 2022). A primary or metastatic malignant neoplasm involving the stomach. "Up to date, our experiment data confirm that BRCAA1 exhibit over-expression in the gastric cancer MGC 803 cells, therefore, we predict that BRCAA1 (ARID4B) may exist in gastric cancer MGC 803 cells with gene mutation or other way, further investigation is still under way." (PMID 26137913, 2015).
glioma (5 papers, 2017 to 2025). A benign or malignant brain and spinal cord tumor that arises from glial cells (astrocytes, oligodendrocytes, ependymal cells). "The AKT-PI3K pathway has been previously linked with ARID4B in prostate cancer and glioma including downregulation of PI3KCA and PI3KR2." (PMID 38137006, 2023). "Overexpression of ARID4B has been detected in a majority of primary brain tumors, and the expression of ARID4B correlated with higher grades of glioma." (PMID 40558499, 2025). "The knockdown of ARID4B in the glioma cell lines LN229 and GMB8401 was shown to significantly reduce glioma cell migration and invasion, accompanied with increased apoptosis." (PMID 40558499, 2025). "In addition, the knockdown of ARID4B induced G1 cell cycle arrest, resulting in decreased glioma cell proliferation via inhibition of the PI3K/AKT pathway and downregulation of cyclin D1 expression." (PMID 40558499, 2025).
prostate carcinoma (5 papers, 2019 to 2025). A carcinoma that arises from epithelial cells of the prostate gland. "On the other hand, ARID4B has been associated with tumor promoter functions regulated by microRNAs in prostate cancer, and others associate it as a tumor suppressor in leukemias." (PMID 38137006, 2023). "Depletion of ARID4B in another PTEN-deficient prostate cancer cell line, LNCaP, significantly suppressed cell growth." (PMID 31551414, 2019). "To determine the functional significance of our findings that ARID4B is a transcriptional activator of the PI3K subunits PIK3CA and PIK3R2, we investigated the role of ARID4B in the development of prostate cancer harboring PTEN deficiency." (PMID 31551414, 2019). "Together, our findings reveal insights into how PTEN controls prostate tumorigenesis, and support the concept that ARID4B is a potential target for interventions in patients with prostate cancer carrying PTEN mutations." (PMID 31551414, 2019). "Collectively, these data demonstrate a synthetic essentiality of ARID4B in prostate cancer elicited by PTEN deficiency." (PMID 31551414, 2019). "Thus, we identified that the PTEN-ARID4B-PI3K regulatory axis underlies the predictive power of the PTEN/ARID4B/PIK3CA signature for tumor recurrence in prostate cancer patients." (PMID 31551414, 2019). "To analyze whether ablation of ARID4B delays the onset of prostate cancer caused by PTEN deficiency, we then examined the PtenPC−/−Arid4bPC−/− mice at 9 months of age." (PMID 31551414, 2019). "Therefore, we examined whether inhibition of ARID4B impairs the tumor-promoting actions in prostate cancer cells driven by loss of PTEN." (PMID 31551414, 2019). "In line with its function in prostate cancer, the knockdown of ARID4B also resulted in a reduced expression of p-AKT and p-mTOR levels." (PMID 40558499, 2025). "In prostate cancer patients, PSA failure, a high Gleason score, and a shorter BCR-free survival were linked with the downregulated expression of ARID4B." (PMID 40558499, 2025). "In the PC3 (PTEN-deficient) cells, knockout of ARID4B efficiently inhibited cancer cell growth and tumor formation in xenografts, suggesting that PTEN-deficient prostate cancer cells depend on ARID4B." (PMID 31551414, 2019). "To determine how ARID4B plays a role in prostate cancer, we performed whole transcriptome analysis (RNA-Seq) to compare gene expression profiles of PC3 cells with or without knockdown of ARID4B." (PMID 31551414, 2019). "In contrast, tumor development in prostates of most of the 5-month-old PtenPC−/−Arid4bPC−/− mice was arrested at the normal, hyperplastic, or low-grade PIN stages, suggesting that ablation of ARID4B attenuated prostate cancer progression." (PMID 31551414, 2019). "The biological significance is further substantiated by the existence of a PTEN/ARID4B/PIK3CA three-gene signature that improves the predictive power for prostate cancer recurrence in patients." (PMID 31551414, 2019). "To determine genomic alterations of ARID4B in prostate cancer, we analyzed the Cancer Genome Atlas (TCGA) and other prostate cancer genomic datasets." (PMID 31551414, 2019). "On the other hand, knockout of ARID4B in the PTEN-intact prostate cancer cell line DU145 only moderately suppressed tumor growth and cell proliferation, and not to the same extent as in PC3 cells." (PMID 31551414, 2019). "Using two prostate cancer gene expression datasets in the Oncomine database, we found that expression of ARID4B was significantly increased in prostate carcinoma (PCa) compared to normal prostate glands." (PMID 31551414, 2019). "This is consistent with results from our Oncomine database analysis, showing increased mRNA levels of ARID4B in human prostate carcinoma compared to normal prostate glands." (PMID 31551414, 2019). "Amplification of ARID4B was detected in up to 20% of human prostate cancer cases (left), while deletion and loss-of-function mutation of PTEN are frequent (right)." (PMID 31551414, 2019).
prostate carcinoma (continued). "Together, these results indicate that ARID4B is required for tumor growth of PTEN-null prostate cancer cells." (PMID 31551414, 2019). "In summary, we identify ARID4B as a master regulator in the PTEN-PI3K pathway, thus providing a potential therapeutic target for prostate cancer carrying PTEN mutations." (PMID 31551414, 2019). "In this study, our data suggest that ARID4B, by directly impinging on the PTEN-PI3K signaling pathway, functions as a synthetic-essential effector for prostate cancer initiation and progression elicited by loss of PTEN." (PMID 31551414, 2019). "We found that the PTEN/ARID4B/PIK3CA three-gene signature had an increased predictive power for prostate cancer recurrence compared to any individual gene alone or two genes combined." (PMID 31551414, 2019). "Recently, a study using prostate-specific Arid4b knockout mouse models showed that ARID4B is essential for the initiation and progression of PTEN-deficient prostate cancer, suggesting the synthetic essentiality of ARID4B in prostate cancer carries PTEN deletion." (PMID 40558499, 2025). "Altogether, the co-downregulation of ARID4A and ARID4B could serve as a prognostic biomarker in prostate cancer patients." (PMID 40558499, 2025). "By analyzing the Cancer Genome Atlas (TCGA) and other prostate cancer genomic datasets, we identified that ARID4B is consistently retained in prostate carcinoma cohorts with deep deletion of PTEN, although deletion of ARID4B also occasionally occurs in prostate cancer." (PMID 31551414, 2019). "Extensive in vitro and in vivo data, including those from depletion of ARID4B in the PTEN-deficient prostate cancer cell line PC3 and the prostate-specific Arid4b and Pten double knockout mouse model, demonstrated that PTEN-deficient prostate cancer depends on ARID4B." (PMID 31551414, 2019). "Therefore, our study demonstrates the synthetic-essential role of ARID4B in PTEN-deficient prostate cancer, and provides the underlying mechanism by which ARID4B is required for executing prostate cancer-promoting actions in the context of PTEN deficiency." (PMID 31551414, 2019). "In addition, while knockdown of ARID4B decreased expression of p110α and p85β in the prostate cancer cell lines PC3, DU145, and LNCaP, knockdown of HDAC1 increased expression of p110α and p85β." (PMID 31551414, 2019). "Furthermore, ARID4B promoter-driven luciferase reporter gene assays showed that knockdown of PTEN activated the ARID4B promoter in the PTEN-intact prostate cancer cell line DU145 and cervical cancer cell line HeLa, whereas overexpression of PTEN suppressed the ARID4B promoter activity." (PMID 31551414, 2019). "Despite these early findings, the role of ARID4B in prostate cancer remains unclear." (PMID 31551414, 2019). "In prostate cancer, miR-30d binds to the 3′ UTR of ARID4A and ARID4B, resulting in the downregulation of these molecules and enhanced cancer progression." (PMID 40558499, 2025). "The HPA database suggested that C18orf25, DYNC1LI2, SYNJ1, MAPK1, and ARID4B are highly expressed in normal tissues, and CLOCK, SETD2, ZNF654, XIAP, MIS18BP1, and MBTPS2 are highly expressed in prostate cancer tissues." (PMID 36249009, 2022). "Together, our results suggest that ARID4B and HDAC1 are likely to function independently to regulate PIK3CA and PIK3R2 in prostate cancer cells." (PMID 31551414, 2019). "Together, these data support the importance of functional interactions between PTEN, ARID4B, and PIK3CA in human prostate cancer." (PMID 31551414, 2019). "Because there tends to be mutual exclusivity between ARID4B and PTEN deletions in prostate cancer genome, ARID4B might be a synthetic-essential gene for prostate tumorigenesis in the context of PTEN deficiency." (PMID 31551414, 2019).